SNHG1 (small nucleolar RNA host gene 1)
Diseases named in the same sentence as SNHG1 in open-access papers (continued):
Sharing a sentence is not in itself a finding about the gene and the disease.
multiple myeloma (2 papers, 2018 to 2022). "Another host gene, SNHG1 encodes eight snoRNAs of which only a handful are up-regulated in multiple myeloma." (PMID 30577491, 2018). "Yet, another type of non-coding RNAs, the long non-coding RNAs (lncRNAs), were also connected to methylation and exosomes in a study on multiple myeloma wherein two lncRNAs, LOC606724 and SNHG1, were reported to be elevated in multiple myeloma cells that were exposed to exosomes from adipocytes." (PMID 35682901, 2022).
osteoarthritis (2 papers, 2019 to 2022). A noninflammatory degenerative joint disease occurring chiefly in older persons, characterized by degeneration of the articular cartilage, hypertrophy of bone at the margins and changes in the synovial membrane. "Long non-coding RNA (LncRNA) small nucleolar RNA host gene 1 (SNHG1) has been reported in the occurrence and development of several diseases, but its biological role and mechanism in osteoarthritis (OA) remain to be illuminated." (PMID 31383786, 2019).
Sepsis (2 papers, 2022 to 2023). Sepsis is defined as life-threatening organ dysfunction caused by a dysregulated host response to infection. "This study aims to investigate the molecular mechanism of long noncoding RNA (lncRNA) small nucleolar RNA host gene 1 (SNHG1)‐mediated DNA methyltransferase 1/B‐cell lymphoma‐2 (DNMT1/Bcl‐2) axis in sepsis‐induced myocardial injury." (PMID 35678255, 2022). "Based on the bioinformatics prediction performed in the current study, the lncRNA small nucleolar RNA host gene 1 (SNHG1) was screened out as a differentially expressed lncRNA in sepsis." (PMID 35678255, 2022). "Therefore, we made a hypothesis in the present study that lncRNA SNHG1 may orchestrate the DNMT1/Bcl‐2 axis to affect the sepsis‐induced myocardial injury." (PMID 35678255, 2022).
thyroid cancer (2 papers, 2022 to 2025). "Functional experiments demonstrated that silencing SNHG1 significantly inhibited the proliferation and invasion of thyroid cancer cells." (PMID 41234719, 2025). "Compared to normal thyroid cells (Nthy-ori-3-1), SNHG1 was also highly expressed in thyroid cancer cell lines IHH4, K1, and TPC1." (PMID 41234719, 2025).
acute lung injury (1 paper, 2023). A condition of lung damage that is characterized by bilateral pulmonary infiltrates (pulmonary edema) rich in neutrophils, and in the absence of clinical heart failure. "Interestingly, SNHG1 is a direct transcriptional target of NFKB subunit p65 that promotes the expression of proinflammatory cytokines in acute lung injury (ALI)." (PMID 37569472, 2023).
angina (1 paper, 2023). "First, expression levels of N1LR and SNHG1 were only tested in AMI patients and healthy volunteers, the situation in patients presented with angina should be verified in future studies." (PMID 37013574, 2023).
atherosclerosis (1 paper, 2020). A disease characterized by the build-up of fatty material and calcium deposition in the arterial wall resulting in partial or complete occlusion of the arterial lumen. "Present study was designed to probe into the biological role of SNHG1 which has been implicated in atherosclerosis-caused cerebral infraction and could regulate cardiovascular disorders." (PMID 32536864, 2020). "On this basis, present study uncovered that SNHG1 attenuated atherosclerosis via up-regulating GNAI2 and PCBP1." (PMID 32536864, 2020).
Atrophy (1 paper, 2019). Any weakening or degeneration, especially through lack of use. "We found that 2310065F04Rik (linc-Myh) resulted down-regulated in both atrophy models while Dancr, Gas5, H19, Igf2os, Airn, MiR22hg, Neat1 and Snhg1 were up-regulated in the late phases of atrophy." (PMID 30649422, 2019).
Barrett esophagus (1 paper, 2025). Esophageal lesion lined with columnar metaplastic epithelium which is flat or villiform. "To further substantiate the clinical relevance of SNHG1 in Barrett’s esophagus progression, we analyzed SNHG1 expression in a well-characterized cohort of BE patients (n = 20) who underwent longitudinal endoscopic surveillance." (PMID 40629071, 2025). "The reversal of EMT phenotypes by RAPA and DAPT further confirms that the effects of SNHG1 are mediated via the ULK1-Notch1 axis, highlighting its potential as a therapeutic target in Barrett’s esophagus." (PMID 40629071, 2025).
bladder tumor (1 paper, 2022). "However, very little information is available about the role and mechanisms of SNHG1 in bladder tumor formation and progression." (PMID 36077697, 2022).
cardiac tumors (1 paper, 2021). "Although we did not observe any cardiac tumors in mice treated with Snhg1, the potential for ectopic proliferation requires careful and specific delivery in future clinical development." (PMID 34646377, 2021).
cerebral infarction (1 paper, 2020). An ischemic condition of the brain, producing a persistent focal neurological deficit in the area of distribution of the cerebral arteries. "LncRNA SNHG1 (small nucleolar RNA host gene 1) is a cerebral infarction-associated gene." (PMID 32536864, 2020).
cerebrovascular diseases (1 paper, 2025). "Similarly, in cerebrovascular diseases, SNHG1 may interact with miR-194-5p, influencing related signaling pathways and increasing the occurrence of CI." (PMID 41346419, 2025).
colorectal tumors (1 paper, 2025). "Together, these findings highlight PABPC1L, SNHG17 and SNHG1 as the most promising candidate biomarkers for distinguishing colorectal tumors from adjacent non-tumor tissues, with PABPC1L showing the most favorable balance of sensitivity and specificity." (PMID 41357316, 2025).
COVID-19 (1 paper, 2021). A disease caused by infection with severe acute respiratory syndrome coronavirus 2. "Moreover, we performed further study with finding a similar high-low-high expression pattern of human SNHG1/VPS13D/IL7R/TCF7 in CD8 T cell subsets from PBMC samples of the convalescent COVID-19 patients." (PMID 33758164, 2021).
epilepsy (1 paper, 2023). A brain disorder characterized by episodes of abnormally increased neuronal discharge resulting in transient episodes of sensory or motor neurological dysfunction, or psychic dysfunction. "During epilepsy progression, SNHG1 delays epilepsy progression by regulating the miR-181a/BCL-2 axis in vitro." (PMID 37684619, 2023).
gastric tumor (1 paper, 2021). "Overexpression of small nucleolar RNA host gene 1 (SNHG1), an lncRNA, is linked to the proliferation of gastric tumor cells, whereas the downregulation suppressed colorectal carcinogenesis." (PMID 33641229, 2021).
heart failure (1 paper, 2021). Inability of the heart to pump blood at an adequate rate to meet tissue metabolic requirements. "Altogether, we shed light on the fact that Snhg1 is capable of stimulating cardiac regeneration, which represent as a promising therapeutic target for heart failure." (PMID 34646377, 2021).
hypopharyngeal squamous cell carcinoma (1 paper, 2022). "This study aimed to explore the function and molecular mechanism of long noncoding RNA Small Nucleolar RNA Host Gene 1 (SNHG1) in the development of hypopharyngeal squamous cell carcinoma (HSCC)." (PMID 35836822, 2022).
ischemic stroke (1 paper, 2020). A stroke disorder caused by obstruction of blood flow to the brain, due to thrombotic (local blood clot formation) or embolic (due to a blood clot or other material traveling from another site) event. "Small nucleolar RNA host gene 1 (SNHG1) has a neuro-protective effect mediated by HIF-1α/VEGF signaling in ischemic stroke." (PMID 32536864, 2020).
keloid (1 paper, 2025). An irregularly shaped, elevated mark on the skin caused by deposits of excessive amounts of collagen during wound healing. "For example, the SNHG1/miR-320b/CTNNB1 axis modulates fibroblast migration during keloid formation, while GNAS-AS1 knockdown reduces keloid growth via the miR-188-5p/RUNX2 pathway." (PMID 40943318, 2025).
leukemia (1 paper, 2019). A malignant (clonal) hematologic disorder, involving hematopoietic stem cells and characterized by the presence of primitive or atypical myeloid or lymphoid cells in the bone marrow and the blood. "Given that lncRNAs can function as a competing endogenous RNA to sponging microRNAs (miRNAs), we measured the expressions of several miRNAs that have been reported to be related to leukemia aggressiveness after SNHG1 knockdown." (PMID 31615767, 2019).
malignant glioma (1 paper, 2019). A grade III or grade IV glioma arising from the central nervous system. "The results suggest that the expression level of FOXP2 is associated with SNHG1, and may be involved in the mechanism of SNHG1 on the biological behavior of malignant glioma cells." (PMID 30728054, 2019).
melanoma (1 paper, 2020). A malignant, usually aggressive tumor composed of atypical, neoplastic melanocytes. "However, our study based on profiling of lncRNA expression in melanoma patients indicated that a low expression of SNHG1 seems to be a good marker of DSF." (PMID 32947877, 2020).
metastatic tumors (1 paper, 2023). "In addition, SNHG1 overexpression is more commonly associated with metastatic tumors, suggesting a contribution to metastasis biology." (PMID 37464317, 2023). "In primary tumors, 17% showed altered SNHG1, however, in metastatic tumors, the proportion of altered SNHG1 was 58% (P = 0.0003)." (PMID 37464317, 2023).
oral cancer (1 paper, 2022). "For instance, the lncRNA SNHG1 is significantly upregulated in oral cancer, and its inhibition can suppress oral cancer cell proliferation." (PMID 36338724, 2022). "Current evidence suggests that SNHG1 can regulate oral cancer growth by regulating the miR-421/HMGB2 signaling pathway." (PMID 36338724, 2022).
pituitary cancer (1 paper, 2019). A primary or metastatic malignant neoplasm affecting the pituitary gland. "A recent study reported that lnc-small nucleolar RNA host gene 1 (lnc-SNHG1), an overexpressed lncRNA found in the tumor tissues and cells lines originating from invasive pituitary cancer, directly binds to miR-302/372/373/520 and promotes expression of their common target, TGFBR." (PMID 30935128, 2019).
postmenopausal osteoporosis (1 paper, 2019). Metabolic disorder associated with fractures of the femoral neck, vertebrae, and distal forearm. "Detection of SNHG1 may provide guidance for the diagnosis and treatment of postmenopausal osteoporosis." (PMID 31693735, 2019). "In addition, postmenopausal females with continuously reduced plasma level of SNHG1 may take proper therapies to avoid the development of postmenopausal osteoporosis." (PMID 31693735, 2019). "In addition, our study also showed that detection of plasma SNHG1 may guide the treatment of postmenopausal osteoporosis." (PMID 31693735, 2019). "Therefore, plasma SNHG1 may serve as a predictive biomarker for postmenopausal osteoporosis." (PMID 31693735, 2019). "Our RNA-seq data revealed that SNHG1 was down-regulated in postmenopausal osteoporosis (data not shown), indicating its involvement in this disease." (PMID 31693735, 2019). "Plasma levels of SNHG1 decreased obviously in females with postmenopausal osteoporosis but not in healthy postmenopausal females." (PMID 31693735, 2019). "Our RNA-seq data revealed that SNHG1 was down-regulated in postmenopausal osteoporosis (data not shown)." (PMID 31693735, 2019).
sarcoma (1 paper, 2022). A usually aggressive malignant neoplasm of the soft tissue or bone. "The forest plot shows that AC004076.2, AC022973.4, YEATS2-AS1, AP000692.1, ITGA6-AS1, AL139289.1, FIRRE, AC008735.2, AL031985.3, AC026271.3, and SNHG1 are risk factors with HR (hazard ratio) > 1, while LINC02447 and AC087645.2 are protective factors with HR < 1 in sarcoma patients." (PMID 35669241, 2022). "Here, we found that SNHG1, FIRRE, and YEATS2-AS1 could serve as biomarkers to predict overall survival of sarcoma patients, which provides a new insight into treatment of STS." (PMID 35669241, 2022).
testicular germ cell tumor (1 paper, 2021). A germ cell tumor arising from the testis. "SNHG1 plays key roles in several tumors such as testicular germ cell tumors and OC." (PMID 33641229, 2021).
transient cerebral ischemia (1 paper, 2025). "We detected the expression levels of SNHG1 and miR-194-5p in the serum of patients with transient cerebral ischemia and constructed a combined prediction model by integrating carotid ultrasound findings." (PMID 41346419, 2025). "However, the expression level of SNHG1 in patients with transient cerebral ischemia and its relationship with the occurrence of CI have not yet been reported." (PMID 41346419, 2025).
cancer (129 papers, 2017 to 2026). A tumor composed of atypical neoplastic, often pleomorphic cells that invade other tissues. "Of interest, SNHG1 was highly expressed in plasma samples from lung and liver cancers and has potential as a diagnostic marker for tumors, reflecting the importance of SNHG1 in tumor circulating transport." (PMID 41507135, 2026). "SNHG1, another lncRNA, was first identified by its oncogenic promotion in cancer cell proliferation, and an increased level of SNHG1 was associated with decreased survival rate." (PMID 37013574, 2023). "SNHG1 is an oncogenic lncRNA controlling cancer progression, upregulation of which is closely associated with advanced tumor stage, tumor size, TNM stage, and decreased overall survival." (PMID 35836822, 2022). "Module M3 includes lncRNA SNHG1, which has been previously linked to neuroinflammation in Parkinson’s disease (PD) and cell proliferation in cancer via miRNA sponging." (PMID 36385761, 2022). "Linked to our results, we demonstrated that the binding of SNHG1 to hnRNPL is responsible for a part of its cancer-promoting features in PCa." (PMID 33542227, 2021). "SNHG1 contributes to cell growth and survival in several cancer types, and we also found it connected with other known cancer‐associated lncRNAs, such as GAS5 and SNHG6." (PMID 32460441, 2020). "has indicated that plasma levels of DANCR and SNHG1 in HCC patients correlate significantly with those in cancer tissues, showing strong associations with critical clinical parameters such as microvascular invasion, invasion of the liver capsule, tumor dimensions, TNM staging, and AFP levels." (PMID 41474641, 2026). "Elevated expression of the RNA SNHG1 has been implicated in various forms of cancer." (PMID 38365726, 2024). "Indeed, SNHG1 has been known to be a novel oncogenic lncRNA aberrantly expressed in a number of cancers and was linked to cell growth, migration and invasion." (PMID 34854215, 2022). "To discern the molecular underpinnings of our observed changes in stemness and invasion due to altered SNHG1 expression, we performed Western blotting using antibodies against several proteins implicated in cancer cell stemness and invasion, including SOX2, OCT4, CD133, and Rac1." (PMID 36077697, 2022). "Abnormal SNHG1 expression is associated with cell proliferation and cancer." (PMID 33499863, 2021). "In conclusion, the present results suggest that promoted lncRNA SNHG1 expression levels are associated with OS and lncRNA SNHG1 may be used as a prognostic marker for cancer patients." (PMID 31391030, 2019). "Accumulating evidence suggested that the expression level of long noncoding RNA small nucleolar RNA host gene 1 (lncRNA SNHG1) was upregulated in various cancers, and high expression of SNHG1 was associated with metastasis and prognosis in patients with cancer." (PMID 31008944, 2019). "Moreover, lncRNAs, such as SNHG1, have been associated with cancer malignancy in pan-cancer including medulloblastoma." (PMID 30050750, 2018). "All these results imply a unique role of exosomal SNHG1 in circulating transport and tumor metastasis in cancer patients and suggest the potential of exosomal SNHG1 as a diagnostic and prognostic marker for PCa bone metastasis." (PMID 41507135, 2026). "Among the highly expressed lncRNAs are GAS5 (also known as SNHG2), SNHG1, NORAD, and NEAT1, abundant transcripts implicated in cell-cycle control, cancer progression, DDR, and inflammation, respectively." (PMID 41369348, 2025). "SNHG1 is highly expressed in various malignant tumors and plays a crucial role in tumorigenesis and progression." (PMID 41234719, 2025).